TNFSF15 (TNF superfamily member 15)
Diseases named in the same sentence as TNFSF15 in open-access papers (continued):
Sharing a sentence is not in itself a finding about the gene and the disease.
co-infection (1 paper, 2023). "and C. perfringens co-infection was highly correlated with IFN-α, IFN-γ, IL-4, IL-13, IL-16, LITAF, TGF-β4 and TNFSF15 in the jejunum, indicating that Th2 type cytokines mainly participated in avian NE." (PMID 37240767, 2023).
endothelial dysfunction (1 paper, 2021). In vascular diseases, endothelial dysfunction is a systemic pathological state of the endothelium (the inner lining of blood vessels) and can be broadly defined as an imbalance between vasodilating and vasoconstricting substances produced by (or acting on) the endothelium. "Bella et al42 also found that the TNFSF15–TNFRSF25 axis is upregulated in uVTE and involved in endothelial dysfunction." (PMID 34381164, 2021).
liver cancer (1 paper, 2024). An epithelial or non-epithelial malignant neoplasm that arises from the liver. "In summary, these data suggest the crucial role of miR-141 in liver cancer development via targeting KLK10 and TNFSF-15 and provide miR-141 as an attractive candidate in liver cancer treatment and protection." (PMID 38866875, 2024). "Interestingly, the experimental rats with liver cancer induced by Diethylnitrosamine injection further confirmed the upregulation of miR-141 level, IL-10, and TNF-α and the disturbance in KLK10 and TNFSF-15 gene expression compared with their expression in normal rats." (PMID 38866875, 2024).
liver cirrhosis (1 paper, 2018). "Specific loci, including collagen 1A1, secreted phosphoprotein 1, SPRR3 and TNFSF15, have been confirmed to be hypomethylated, resulting in the up-regulation of these genes in patients with liver cirrhosis of various etiologies." (PMID 30038293, 2018).
lymphoedema (1 paper, 2018). "Further research will determine whether TNFSF15′s unique capacity to regulate the properties of both blood and lymph vessels can be harnessed to improve the treatment of conditions such as cancer, stroke, myocardial infarction and lymphoedema." (PMID 30101034, 2018).
mastitis (1 paper, 2025). Inflammation of breast tissue during lactation or postpartum due to an obstructed duct or infection. "Preliminary findings suggest that Tnfsf15 may serve as a key host molecule regulated by this gene cluster to mediate inflammation and tissue damage during mastitis." (PMID 40611352, 2025). "During mastitis caused by nonlactating S. agalactiae, Tnfsf15 may promote localized inflammation by modulating this immune pathway, leading to mammary cell damage and tissue necrosis." (PMID 40611352, 2025). "The Tnfsf15 gene may play a critical role in the inflammatory damage caused by nonlactating S. agalactiae in mastitis." (PMID 40611352, 2025). "However, this is only our preliminary hypothesis, and the molecular connection between Tnfsf15 and the pilus-associated gene cluster of nonlactating S. agalactiae in mastitis will be further elucidated in subsequent studies." (PMID 40611352, 2025).
oral cavity squamous cell carcinoma (1 paper, 2022). A squamous cell carcinoma arising from the oral cavity. "However, the roles of TNFSF15 single‐nucleotide variants (SNVs; formerly SNPs) in oral cavity squamous cell carcinoma (OCSCC) remain unclear." (PMID 36226563, 2022).
preeclampsia (1 paper, 2015). Preeclampsia is a hypertensive disorder of pregnancy that is characterized by new-onset hypertension with proteinuria presenting after 20 weeks of gestation, and depending on mild or severe forms may initially present with severe headache, visual disturbances, and hyperreflexia. "In preeclampsia, both TNFSF15 and sFLT1 act as anti-angiogenic proteins contributing to placental dysfunction." (PMID 25799546, 2015). "Although TNFSF15 has been largely unstudied in the fields of pregnancy, preeclampsia and placental biology, these results provide some evidence that TNFSF15 may be contributing to the regulation of sFLT1 in trophoblast cells." (PMID 25799546, 2015).
proliferative diabetic retinopathy (1 paper, 2016). Advanced retinopathy due to diabetes mellitus characterized by the formation of new vessels in the retina. "Vitreous TNFSF15 and VEGF levels in proliferative diabetic retinopathy (PDR) patients were detected by ELISA." (PMID 27120595, 2016).
Pruritus (1 paper, 2022). Pruritus is an itch or a sensation that makes a person want to scratch. "We identified several pruritus-associated genes increased by IDL, IDC and IDL + IDC (e.g., BRCA2, KRT5, TCF4), as well as several such genes decreased by IDL, IDC and/or IDL + IDC (e.g., IL2RG, TRPV3, TNFSF15, IL17RC)." (PMID 36430783, 2022).
pulmonary hypertension (1 paper, 2014). Increased pressure within the pulmonary circulation due to lung or heart disorder. "Thus, it might be expected that TNFSF15 gene expression has increased in patients with pulmonary hypertension." (PMID 25330517, 2014). "Further studies on larger groups are needed to determine the function of TNFSF15 in SCD patients with ACS and pulmonary hypertension." (PMID 25330517, 2014). "Further studies on larger groups are needed in order to appreciate the function of TNFSF15 in SCD patients with ACS and pulmonary hypertension." (PMID 25330517, 2014). "Since there was no patient with SCD and pulmonary hypertension in our study population, we could not research the relation between the TNFSF15 gene and pulmonary hypertension." (PMID 25330517, 2014).
skin cutaneous melanoma (1 paper, 2023). "In skin cutaneous melanoma (SKCM), cancers with high expression of IL1B, CCL5, CXCL10, and TNFSF15 exhibited better prognoses." (PMID 37980406, 2023).
thyroid cancer (1 paper, 2025). "Furthermore, prognostic ROC curves based on the GEO validation set demonstrated that CYP1B1, GABRB2, and TNFSF15 were significantly associated with thyroid cancer diagnosis (AUC exceeding 0.86)." (PMID 40900788, 2025). "CYP1B1, GABRB2, and TNFSF15 have been identified as significant target genes that can collectively predict the prognosis of thyroid cancer and possess high clinical value." (PMID 40900788, 2025). "Through computational network toxicology analysis, this study identifies CYP1B1, GABRB2, and TNFSF15 as potential molecular targets mediating DEHP’s effects in thyroid cancer." (PMID 40900788, 2025).
tumor (59 papers, 2012 to 2025). "In contrast, low-risk tumors exhibited higher expression of HHLA2, NRP1 and TNFSF15, which are associated with a more balanced immune response and anti-tumor activity." (PMID 40243888, 2025). "Studies have shown that over-expression of TNFSF15 inhibits tumor growth in various cancers whereas reduced expression of TNFSF15 is associated with poor prognosis in cancer patients." (PMID 30736740, 2019). "One of the underlying mechanisms is the induction of TNFSF15, an important negative regulator of tumor angiogenesis." (PMID 26717043, 2016). "In addition, CD48, CTLA4, HHLA2, TNFSF9, and TNFSF15 were elevated in high-risk group, suggesting that the high-risk group are more likely to show immunosuppressive phenotype in tumor microenvironment." (PMID 37903974, 2023). "Furthermore, treatment of tumor-bearing mice with recombinant TNFSF15 enhances the association of myeloid cell-derived pericytes with endothelial cells in tumor vessels, thereby normalizing the wall structure of the new blood vessels." (PMID 37921408, 2023). "The low-risk group exhibited significantly elevated expression levels of HHLA2, NRP1, and TNFSF15, suggesting a less immunosuppressive tumor microenvironment." (PMID 40243888, 2025). "In summary, our study proposes the following model: knockdown of APRC4 or NDUFV1 in GBM cells leads to the upregulation of the immuno-stimulatory factor TNFSF15 in tumor cells." (PMID 38561797, 2024). "The macrophages recruit the T cells, including the Treg and Th1 helper cells via VEGI (TNFSF15) signalling, and it has been shown that TNFSF15 promotes macrophage polarisation toward M1 for tumour suppression." (PMID 39149248, 2024). "TNFSF15 treatment under these experimental conditions retarded tumor growth in the first 2 weeks of the treatment period." (PMID 37921408, 2023). "IL17C and TNFSF15 are involved in tumorigenesis and development by impacting immune cell function, and MIA is associated with tumor invasion." (PMID 36936375, 2023). "The expression of TNFSF15 in ccRCC was markedly decreased and was more likely to be a tumor-suppressive factor." (PMID 34537809, 2021). "We present, to our knowledge, the first bifunctional TNF-like ligand 1A (TL1A/TNFSF15) fusion proteins to deliver tumor-targeted co-stimulation." (PMID 34484225, 2021). "Systemic administration of recombinant TNFSF15 results in an inhibition of tumor angiogenesis and tumor growth in animal models." (PMID 28097093, 2017). "We have shown that LITAF acts as transcriptional factor to activate transcription of TNFSF15, so as to inhibit tumor angiogenesis." (PMID 26717043, 2016). "Among the highly up-regulated trancripts in T24MshPFN1 cells (5.18-fold) was Tumor necrosis factor ligand superfamily member-15 (TNFSF15), an angiogenesis inhibitor that suppress tumor growth." (PMID 27683119, 2016). "TNFSF15 is involved in numerous cellular processes including the suppression of neovascularization which is essential for tumor progression and spread." (PMID 25251497, 2014). "In conjunction, intratumoural injection of TNFSF15 significantly reduces the size of tumours and number of blood vessels." (PMID 23414097, 2013). "Furthermore, significant differences in the expression of immune checkpoints—specifically CD200, CD274 (PD-L1), TIGIT, TNFRSF25, and TNFSF15—were observed between tumor and normal samples." (PMID 40666524, 2025). "Finally, we demonstrated an immunostimulatory role of TNFSF15 in modulating tumor-CAR T interaction to enhance CAR T cell anti-tumor activity." (PMID 38561797, 2024). "Moreover, the addition of recombinant trimeric TNFSF15 protein into CAR T-tumor coculture significantly promoted tumor killing by CAR T cells in an antigen-specific and dose-dependent manner." (PMID 38561797, 2024).
tumor (continued). "This process also occurs in vivo, because treatment of the mouse LLC tumor model with TNFSF15 enhanced the CD11b+ cell population percentage in the bone marrow, and significantly increased the percentage of tumor-infiltrated pericytes and their association with vascular endothelial cells." (PMID 37921408, 2023). "Thus, TNFSF15 treatment of the tumor-bearing animals enhanced the accumulation of CD11b+ cells in tumors." (PMID 37921408, 2023). "It is interesting to note that TNFSF15 gene expression is almost totally down-regulated in proliferative endothelium and in tumor vasculatures and that may increase the maturation and polarization of macrophages toward a tumor-killing M1 type." (PMID 36429070, 2022). "Some studies have shown that high TNFSF15 levels in cancers decrease the growth of the tumor." (PMID 36429070, 2022). "In addition, in our study, DNA was extracted from different specimens to sequence TNFSF15 SNVs, including the whole blood of all the enrolled participants and the tumour tissue specimens from the TCGA database." (PMID 36226563, 2022). "Other studies reported that IL-37, LECT2, and TNFSF15 suppress tumor growth." (PMID 35563525, 2022). "Additionally, we found that LITAF participates in transcriptional regulation of TNFSF15, a pro-inflammatory cytokine and also a potent inhibitor of tumor angiogenesis." (PMID 26717043, 2016). "The TNFSF15 protein also inhibits the tumor growth in murine tumor models." (PMID 25251497, 2014). "Recent studies point to a possible anti-tumor role of TNFSF15." (PMID 25251497, 2014). "Over-expression of TNFSF15 gene has been shown to inhibit the development of multiple tumor types." (PMID 25251497, 2014). "VEGI, also known as tumor necrosis factor superfamily member 15 (TNFSF15) or TNF ligand related molecule 1 (TL1), is a cytokine with potent anti-angiogenic properties principally studied in cancer as an inhibitor of endothelial cell proliferation and tumor growth." (PMID 22409996, 2012). "TNFSF15 facilitates the production of CD11b+ cells in the bone marrow and promotes the differentiation of these cells into pericytes, which may stabilize the tumor neovasculature." (PMID 37921408, 2023). "In addition to coactivating T cells and stimulating dendritic cell maturation, some studies reported that in the tumour, TNFSF15 might promote lymphatic metastasis through assisting lymphangiogenesis." (PMID 36226563, 2022). "An analysis of these immune checkpoints in tumor and normal samples revealed significant differences in the expression of CD200, CD274, TIGIT, TNFRSF25, and TNFSF15 between the two groups (P < 0.05)." (PMID 40666524, 2025). "Simultaneously, SPP1 downregulated CD40LG, TNFSF15, TNFRSF13B, IL6R, KLRK1, and other immune stimulants, indicating that SPP1 played a role in the evasion of tumor immunity by controlling the immunosuppressive surroundings." (PMID 38329443, 2024). "Three hub genes (IL17C, TNFSF15, and MIA) related to tumor immunity and metastasis were identified by WGCNA, and the abnormal expression of each hub gene in ESCA has a poor prognosis, especially in patients with high expression (P < 0.05)." (PMID 36936375, 2023). "The expressions of IL17C, TNFSF15, and MIA in tumor tissues were significantly different from those in adjacent tissues." (PMID 36936375, 2023). "On this basis, IL17C, TNFSF15, and MIA which were related to tumor immunity, invasion, and metastasis were identified." (PMID 36936375, 2023). "We demonstrated that P4HA1 expression was positively correlated with the expression of TNFSF15, CD80, VTCN1, TNFSF18, and CD200R1 in multiple tumor types but negatively correlated with the expression of CD40LG and CD244." (PMID 35812752, 2022). "Therefore, TNFSF15 might improve the tumor progression to a certain extent." (PMID 35847907, 2022). "TNFSF15 can also suppress endothelial cell proliferation and angiogenesis through the binding of DR3, and this was verified in a mouse xenograft tumor model." (PMID 35311155, 2022).
tumor (continued). "Immune checkpoint molecules, such as CTLA4, NRP1, TNFSF15, CD44, and BTLA, are present in the TME or on the surface of tumor cells, and they negatively regulate T cell activation." (PMID 34926701, 2021). "The high-response group exhibited elevated expressions of BTLA, LGALS9, PDCD1LG2, TIGIT, TNFSF15, and VTCN1 compared to the low-response group, suggesting that patients with this tumor profile may benefit from ICIs therapy." (PMID 40761787, 2025). "Furthermore, we discovered that TNFSF15 was upregulated in both ARPC4 and NDUFV1 knockdown GBM cells and revealed an immunostimulatory role of TNFSF15 in modulating tumor-CAR T interaction to enhance CAR T cell efficacy." (PMID 38561797, 2024). "JAG1-NOTCH1 and TNFSF15-TNFRSF25 signals were present between tumor cells and low-risk T cells, and absent between tumor cells and high-risk T cells." (PMID 37120631, 2023). "We found that the costimulatory molecules TNFSF15 and TNFSF9 were overexpressed in the siGPX4 group, suggesting that GPX4 knockdown could inhibit tumor angiogenesis." (PMID 37649598, 2023). "Conversely, TBRG4 showed a negative correlation with CD96 and TNFSF15 (P < 0.05, R < −0.1), suggesting it may influence pathways that inhibit T cell function, thereby fostering a more immunosuppressive tumor microenvironment." (PMID 40260662, 2025). "Thus, the upregulated TNFSF15 in tumor cells upon APRC4 and NDUFV1 knockdown may serve as an immune-stimulatory factor for CAR T cells, facilitating their tumor lytic activity." (PMID 38561797, 2024). "However, the binding of TNFSF15 to its receptor, TNFRSF25, amplifies the expression of IL-4, IL-6, GM-CSF, and IL-1758,59, which may explain the overactivity of these tumour-promoting cytokines in our network." (PMID 29062084, 2017). "In contrast, CDH18 showed negative correlations with TNFSF14, TNFSF15, PDCD1, TNFRSF14, and CD44, genes reported to play critical roles in tumor inhibition." (PMID 40017628, 2025).
cancer (40 papers, 2012 to 2025). A tumor composed of atypical neoplastic, often pleomorphic cells that invade other tissues. "Till now, a few studies have been carried out to demonstrate the association of TNFSF15 polymorphisms with the susceptibility to cancer." (PMID 30736740, 2019). "Our findings suggest that miR‐20a and miR‐31 are potentially oncogenic as they cause a repression of the expression of TNFSF15 gene, which appears to be able to function as a gate‐keeper of neovascularization in cancers." (PMID 28097093, 2017). "For instance, it has been shown that recombinant TNFSF15 exhibits anti-neoplastic effects by inhibiting angiogenesis and TNFSF15 overexpression was associated with improved cancer prognosis." (PMID 25251497, 2014). "Additionally, two immunostimulators were associated with ZNF714 expression in a pan-cancer manner, namely, Tumor Necrosis Factor Superfamily Member 15 (TNFSF15) and UL16 Binding Protein, a ligand activating NK and T cells (ULBP1)." (PMID 37958512, 2023). "TNFSF15 SNVs, such as rs3810936, rs6478108 and rs6478109, have also been reported to be significantly associated with the development of inflammatory diseases and increasing cancer development." (PMID 36226563, 2022). "Moreover, little or nothing is known about the effects of these TNFSF15 polymorphisms on human cancer susceptibility." (PMID 25251497, 2014). "Since genetic variants may have different influences on TNFSF15 expression, that ethnic differences in the distribution of TNFSF15 genetic variants might partially correlate with their different effects on cancer phenotypes within these populations." (PMID 25251497, 2014). "In contrast, a uniform negative association with PEBP1/STK11 co-expression was found in most of the genes encoding TNF ligands (ENFSF13B, TNFSF4, TNFSF9, TNFSF14, TNFSF18, and TNFSF15) in almost all cancer types." (PMID 40806276, 2025). "Heatmap analyses revealed that GPATCH3 expression was broadly negatively correlated with chemokines such as CXCL5 and CXCL8, as well as immunostimulatory molecules including CD40LG and TNFSF15, in a pan-cancer context." (PMID 40861452, 2025). "TL1A (TNFSF15) binds to death receptor 3 (DR3) on cancer cells, where it induces apoptosis, and also acts on immune cells to promote anti-angiogenesis and macrophage M1 polarization." (PMID 40564222, 2025). "LITAF is a downstream target of AMPK that inhibits cancer cell growth by increasing the expression of TNFSF15 and inhibiting angiogenesis." (PMID 39684426, 2024). "And especially, USP28 was significantly correlated with NRP1, CD276, ADORA2A, and TNFSF15 in most cancers." (PMID 37450415, 2023). "The effects of TNFSF15 rs3810936, rs6478108 and rs6478109 on cancer development and prognosis were analysed by real‐time PCR genotype assay." (PMID 36226563, 2022). "TL1A/TNFSF15 was initially identified as a factor inducing vascular endothelial cell apoptosis and this finding has been extended to immune cells, cancers and, in this study, to hippocampal neurons." (PMID 32139808, 2021). "Looking at the top 5 coding mutations, for example, we noted that corresponding genes (FES, TNFSF15, MSRB1, HRAS, and SLC1A7) have all been experimentally implicated in cancer as drivers." (PMID 32859160, 2020). "Recently, TNFSF15 was also recognized as a valuable potential therapeutic target for cancer therapy." (PMID 25251497, 2014). "It’s important to note that the role of TNFSF15 in immunotherapy is still an active area of investigation, and its significance may vary depending on the cancer type and individual patient characteristics." (PMID 38590525, 2024). "ETS2 was positively correlated with CD200, NRP1, ICOSLG, and TNFSF15 across several cancers." (PMID 36760475, 2023). "Although TNFSF15 was significantly related to tissue inflammation and carcinogenesis, the interaction between TNFSF15, tissue inflammation, and cancer development in OCSCC was unknown." (PMID 36226563, 2022).